CCDC188 (coiled-coil domain containing 188)
Tractability: Antibody: UniProt predicts a signal peptide or a membrane-spanning region.
Gene: Protein-coding gene on chromosome 22 (20,148,416 to 20,151,055, reverse strand). Ensembl gene ENSG00000234409.
Subcellular location: Membrane
Subcellular location (Human Protein Atlas): Nuclear bodies; Flagellar centriole; Nucleoplasm
Gene Ontology:
Cellular component: membrane
Genetic constraint (gnomAD): Loss-of-function variants: 37 observed, 42.29 expected, observed/expected ratio (o/e) 0.87, 90% interval 0.67 to 1.15. The upper end of that interval is the gene's LOEUF score, 1.15, which puts it in group 5 of 6, group 1 being the genes least tolerant of losing a copy. Missense variants: 452 observed, 463.16 expected, observed/expected ratio (o/e) 0.98, 90% interval 0.9 to 1.05. Synonymous variants: 207 observed, 207.32 expected, observed/expected ratio (o/e) 1, 90% interval 0.89 to 1.12.
Homologues: Orthologues: chimpanzee CCDC188 (99% identical), dog CCDC188 (77% identical), pig CCDC188 (73% identical), mouse Ccdc188 (68% identical), rat Ccdc188 (61% identical), macaque CCDC188 (60% identical), rabbit CCDC188 (50% identical). Paralogues in human: SMCO2 (13% identical), TMCO5A (12% identical).
Diseases named in the same sentence as CCDC188 in open-access papers:
CCDC188 is named in the same sentence as 4 diseases in open-access papers, as found by Europe PMC text mining. Sharing a sentence is not in itself a finding about the gene and the disease. The quoted sentences say what the papers report.
infertile (2 papers, 2024 to 2025). "In the previous study, ASS syndrome of infertile patients with nonsense variant in CCDC188 was caused by a break between the nucleus and the proximal centriole." (PMID 39292630, 2025). "Ccdc188 is essential for a tight linkage between the sperm head and neck, and loss of CCDC188 leads to infertility in male mice due to acephalic spermatozoa with motility defects." (PMID 39292630, 2025). "Based on our attempts in mice, we suggest that CCDC188 mutation-associated infertility in humans is likely overcome by ICSI treatment." (PMID 38616611, 2024). "In summary, we identified a homozygous nonsense variant, c.937C > T/p.R313*, in CCDC188 gene using WES in a consanguineous family with an infertile proband suffering from ASS." (PMID 38616611, 2024).
male infertility (2 papers, 2024 to 2025). The inability of the male to effect fertilization of an ovum after a specified period of unprotected intercourse. "To reveal the cause(s) of male infertility in Ccdc188 KO mice, we observed spermatozoa obtained from Ccdc188 KO cauda epididymis." (PMID 39292630, 2025). "In summary, disruption of Ccdc188 leads to the production of acephalic spermatozoa without a mitochondrial sheath and abnormal sperm motility, which are the causes of Ccdc188 KO male infertility." (PMID 39292630, 2025). "CCDC188 was specifically expressed at the HTCA of human and mouse sperm and Ccdc188-KO mice exhibited male infertility with a typical ASS phenotype." (PMID 38616611, 2024). "In a previous study, a homozygous nonsense variant in CCDC188 was detected in an ASS patient, and mice lacking Ccdc188 exhibited male infertility with acephalic spermatozoa." (PMID 39292630, 2025).
sterility (1 paper, 2025). "Whereas Ccdc188 KO adult females were fertile, Ccdc188 KO male mice showed sterility." (PMID 39292630, 2025).
CCDC188 also shares sentences with these, for which no sentence is quoted: acephalic spermatozoa syndrome (1 paper).